RNU6-920P (RNA, U6 small nuclear 920, pseudogene)
Gene: Small nuclear RNA gene on chromosome 17 (29,641,611 to 29,641,702, reverse strand). Ensembl gene ENSG00000222858.
Homologues: Orthologues: chimpanzee U6 (100% identical), macaque U6 (96% identical), guinea pig U6 (65% identical). Paralogues in human: RNU6-1103P (83% identical), RNU6-1127P (83% identical), RNU6-15P (83% identical), RNU6-188P (83% identical), RNU6-196P (83% identical), RNU6-21P (83% identical), RNU6-38P (83% identical), RNU6-88P (83% identical), RNU6-937P (83% identical), RNU6-95P (83% identical), RNU6-1 (82% identical), RNU6-1024P (82% identical), and 1284 more.